IRF1 (interferon regulatory factor 1)
Diseases named in the same sentence as IRF1 in open-access papers (continued):
Sharing a sentence is not in itself a finding about the gene and the disease.
leukemia (15 papers, 2013 to 2025). A malignant (clonal) hematologic disorder, involving hematopoietic stem cells and characterized by the presence of primitive or atypical myeloid or lymphoid cells in the bone marrow and the blood. "The loss of IRF-1 expression has been observed in several cases of leukemia." (PMID 31244811, 2019). "Research on leukemia has shown that IRF1 is highly expressed in AML stem cells, patient samples, and cell lines, and is correlated with poor prognosis." (PMID 40025540, 2025). "Considering the potential involvement of IRF1 in leukemia, we conducted IRF1 expression level–based stratification of human AML." (PMID 37889967, 2023). "The IRF‐1 gene is located in the chromosome 5q31 region, where its deletion is a prominent feature of many leukemias." (PMID 32617521, 2020). "This makes IRF‐1 a molecule of interest to study for its role in RA‐induced leukemia cell differentiation." (PMID 32617521, 2020). "This study highlighted the importance of IRF‐1 in directly regulating p47phox expression and O2– production in mature leukemia cells." (PMID 32617521, 2020). "To confirm these results, we selected three key genes involved in leukemia (interferon-regulatory factor 1 [IRF1], Caspase 8, and specificity protein 1 [SP1]) to confirm the gene expression of those factors was regulated by USP39." (PMID 30898977, 2019). "Once the IRF-1 locus had been determined, a full-length IRF-1 cDNA probe was used to perform Southern blotting of DNA from patients with different types of leukemia and MDS associated with del(5q) to confirm IRF-1 inactivation in clinical samples." (PMID 29599126, 2018). "Our theoretical analysis suggests that the dynamics of the final gene of this chain (IRF1) is highly constrained by the LRC, and biological experimentation indicates that IRF1 is a tumour suppressor gene relevant to a number of cancers including leukaemia." (PMID 28575450, 2017). "Specific splicing aberrations of the IRF-1 gene leads to loss of functional IRF-1 in MDS and leukemias." (PMID 23420765, 2013). "However, some lymphoid leukemias exhibited significant up-regulation of IRF1, and IRF1 expression varied substantially between patients within all leukemia subclasses." (PMID 37889967, 2023). "Moreover, our observation that IRF1 expression differs substantially between patients within various leukemia subclasses supports the use of IRF1 as a broad leukemia stratification marker." (PMID 37889967, 2023). "In addition, given the frequent abnormal expression of IRF1 in leukemia, we explored the potential of IRF1 expression level as a stratification marker for human acute myeloid leukemia." (PMID 37889967, 2023). "IRF‐1 acts as a tumor suppressor in various types of cancer, especially in human leukemia." (PMID 32617521, 2020). "Knockdown or IRF1 partially restored the proliferation rate of leukemia cells with USP39 knockdown." (PMID 30898977, 2019). "Furthermore, we performed a microarray assay and found that USP39 regulated the expression of diverse genes in human leukemia cells, including IRF1, Caspase 8, and SP1, which were validated by qRT-PCR experiments." (PMID 30898977, 2019). "Following the discovery of a role for IRF-1 in human leukemia and pre-leukemic myelodysplasia, researchers began to question whether it and other IRF family members might be similarly implicated in other cancers, particularly solid tumors." (PMID 29599126, 2018). "This led to the conclusion that deletions or rearrangements are more frequent than point mutations at this locus in human leukemia and MDS, and loss of IRF-1 may be critical in the development of AML and MDS." (PMID 29599126, 2018). "Clinical data have shown that IRF-1 expression is lost in many cases of leukemia." (PMID 25389759, 2014). "Deletions or rearrangements of the IRF-1 tumor suppressor gene and exon skipping of the IRF-1 full-length wild type (IRF-1 WT) transcript have been described in patients with myelodysplastic syndromes (MDS) and leukemia." (PMID 40862725, 2025).
psoriasis (15 papers, 2009 to 2025). An autoimmune condition characterized by red, well-delineated plaques with silvery scales that are usually on the extensor surfaces and scalp. "Simultaneously, IDMF represses pro-inflammatory transcription factors, including NF-κB, AP-1, and potentially IRF1, leading to the downregulation of key psoriasis-associated cytokines such as IL-17A, IL-23A, IL-36G, and IFN-γ." (PMID 41465291, 2025). "In parallel, IDMF suppresses NF-κB, AP-1, IRF1, and STAT-linked pathways, thereby downregulating IL-17A, IL-23A, IL-36G, IFN-γ, and other psoriasis-associated cytokines at their transcriptional origins." (PMID 41465291, 2025). "UVB repressed Oct1, an IFN-γ-independent transcription factor for HLA-C that modulates HLA-C expression and, similar to STAT1 and IRF1, is a transcriptional regulator of differentially expressed genes in psoriasis lesions." (PMID 40243413, 2025). "Genes co-expressed with B3GNT2 in macrophages were located next to intergenic sequences with elevated density of motifs recognized by TFs important to psoriasis pathogenesis, such as IRF1, STAT4 and STAT5 (Part B)." (PMID 24885462, 2014). "Recent studies indicated that IRF1 could mediate M1 polarization of macrophages which may contribute to psoriasis." (PMID 36059983, 2022). "After that, genetically, the variation at the IRF2 gene but not IRF1 gene was found to be associated with susceptibility to psoriasis." (PMID 32456211, 2020). "Concerning psoriasis, IRF1 and IRF2 are the most studied IRFs." (PMID 32456211, 2020). "Our results suggest new hypotheses for interpretation of intergenic hits from psoriasis GWAS studies, and we have identified SNPs predicted to influence binding of AP-1, NF-κB, IRF1, STAT3 and STAT4." (PMID 24885462, 2014). "Some of these proteins (IRF-1, PKC-beta) were already linked to psoriasis in other independent studies, while others (CaMKII, PKC-delta) may represent novel targets." (PMID 19309513, 2009). "The identification of IRF1, a dual regulator of autophagy and apoptosis in response to bevacizumab treatment, as one of the top activated upstream regulators in non‐lesional skin, re‐enforces the hypothesis that IRF1 mediates the anti‐apoptotic effect of bevacizumab in non‐lesional psoriasis skin." (PMID 39624732, 2024). "We show that PREs can be strategically combined to create a cdODN concomitantly targeting psoriasis-activated TFs (FOXM1, ISGF3, IRF1 and NF-κB), illustrating how transcriptome informatics can be directly connected to dODN development." (PMID 25883770, 2015). "To illustrate this idea, we designed a cdODN to concomitantly target psoriasis-activated TFs (i.e., FOXM1, ISGF3, IRF1 and NF-kappaB)." (PMID 25883770, 2015). "To design a candidate cdODN for psoriasis treatment, we focused on a limited set of TFs (FOXM1, IRF1 and NF-κB) as well as the IFN-stimulated gene factor 3 (ISGF3) complex (i.e., STAT1, STAT2 and IRF9)." (PMID 25883770, 2015). "IRF1 has been observed throughout the epidermis in both normal skin and psoriatic lesions 40, but one study reported that IRF1 expression is lower in psoriatic lesions than in non-lesions of patients with psoriasis or normal skin." (PMID 34790055, 2021). "While IFN-gamma, IRF-1 and CBP were already associated with psoriasis in independent studies, there is no direct evidence in the literature regarding involvement of PKC-delta and CaMKII in the disease." (PMID 19309513, 2009). "TFAM mRNA was not differentially expressed in psoriasis lesions (FC = 0.98, P = 0.366), but the TFAM motif contained elements similar to those present in IRF1, ISGF3 and NF-κB recognition sites." (PMID 25883770, 2015). "Although cdODN199 includes FOXM1, ISGF3, IRF1 and NF-κB recognition sites, it does not include a binding site for STAT3, previously validated as an effective dODN target in a psoriasis mouse model." (PMID 25883770, 2015).
prostate carcinoma (14 papers, 2016 to 2024). A carcinoma that arises from epithelial cells of the prostate gland. "This complex inhibits interferon regulatory factor 1 (IRF1), a tumor suppressor, to promote the proliferation of different prostate cancer cell lines." (PMID 38734665, 2024). "The overexpression of DTX3L promotes the phosphorylation of STAT1 and represses the transcription of IFN regulatory factor-1 (IRF-1), thus enhancing the proliferation, metastasis and chemoresistance of prostate cancer cells." (PMID 36614304, 2023). "The ameliorative effect of SeNPs in prostate cancer was indicated by overexpression of necroptosis related to IRF1 and TNF, a decrease in expression of PSA and AR, and an increase in ROS-mediated necroptosis in PC-3 cells." (PMID 36290639, 2022). "The overexpression of DTX3L and BAL1 promotes the phosphorylation of STAT1 and represses the transcription of IFN regulatory factor-1 (IRF-1), thus enhancing the proliferation, metastasis, and chemoresistance of prostate cancer cells." (PMID 34513839, 2021). "Bacillus licheniformis derived biogenic SeNPs are very effective in inducing prostate cancer cell death at a minimum concentration of 2 μg Se/ml through a TNF/IRF1 mediated necroptosis pathway and by AR down-regulation." (PMID 32010628, 2019). "However, Se nanoparticles reversely promoted ROS-mediated necroptosis with via upregulating TNF and interferon regulatory factor 1 (IRF1) in prostate cancer cells." (PMID 36211509, 2022). "This occurs via activation of the STAT1/3-mediated regulation of IRF1 (interferon regulatory factor 1) in NSCLC, prostate cancer, and osteosarcoma." (PMID 38473324, 2024). "These included 8 genes differentially expressed in lethal prostate cancer and highly functionally related to NFκB along with additional promising candidates such as CXCL1, KLF6, and IRF1." (PMID 27078000, 2016). "Notable genes in the predicted pathway included ATF3, JUNB, KLF6, NR4A2, ZFP36, DUSP5 and NEDD9, as well as STAT3 and IRF1 as novel upstream regulators, and SELE, CXCL1 and CXCL2 as novel downstream targets of NFκB in prostate cancer." (PMID 27078000, 2016). "IFN-γ stimulating the IFNGR1 receptor complex induces the transcription factors including Signal Transducer and Activator of Transcription 1 (STAT1) and Interferon Regulatory Factor 1 (IRF1) to actuate the type II IFN response genes and chronic inflammatory reaction in prostate carcinoma cells." (PMID 35814468, 2022).
Sepsis (12 papers, 2016 to 2025). Sepsis is defined as life-threatening organ dysfunction caused by a dysregulated host response to infection. "As a master regulator of IFN signaling and immune homeostasis, IRF1 presents a promising yet dual-edged target for therapeutic intervention of sepsis-associated ARDS." (PMID 40420582, 2025). "In summary, the current study identified IRF1 as a promising biomarker for sepsis-associated ARDS risk and survival, with these effects largely mediated by the downstream HLA-F gene." (PMID 40420582, 2025). "Other transcripts upregulated in CD5L− peritoneal cells, including Osm, Il18bp, Ripk1, Nub1, Tlr2, Stat1, Irf1, Nfkb1, Pik3r5, or their coding proteins, were already associated with sepsis severity." (PMID 38750020, 2024). "Our findings suggest that early prophylactic intervention to activate IRF1 in sepsis patients may reduce the risk of ARDS development and mortality, especially among those with severe illness." (PMID 40420582, 2025). "Early prophylactic interventions to activate IRF1 in sepsis patients, thereby regulating HLA-F, may reduce the risk of ARDS and mortality, especially in severely ill patients." (PMID 40420582, 2025). "It has been shown that HDAC6 can activate STAT1 by promoting phosphorylation at Y701 of STAT1, which further increases interferon-regulatory factor-1 (IRF-1) expression, leading to increased iNOS levels in LPS-activated macrophages, thus promoting sepsis-associated ALI." (PMID 37175583, 2023). "This is consistent with our findings, in which higher IRF1 expression at ICU admission is associated with reduced ARDS risk and improved survival among sepsis patients." (PMID 40420582, 2025). "Transcriptional network analysis showed that NFκB, Jun and Irf1 mainly regulate the expression of genes in LPS-induced sepsis." (PMID 37510271, 2023). "The study identified seven important PRGs including CHMP7, NLRC4, PLCG1, IRF1, CASP4, NLRP1, GSDMD associated with sepsis." (PMID 37939116, 2023). "Our findings suggest that early prophylactic interventions to activate IRF1 might be promising for reducing the risk of ARDS development and mortality, particularly in severely ill sepsis patients." (PMID 40420582, 2025). "Additionally, a significant protective effect of IRF1 on the survival of sepsis patients was also observed in the MARS cohort (HRper 1-SD = 0.76, 95% CI: 0.62 to 0.93, P = 0.008; HRHigh vs. Low = 0.64, 95% CI: 0.44 to 0.95, P = 0.025)." (PMID 40420582, 2025). "Furthermore, individual-level measured IRF1 expression was associated with reduced ARDS risk (OR = 0.58, P = 8.67 × 10−4), and improved overall survival in ARDS patients (hazard ratio [HR28-day] = 0.49, P = 0.009) and sepsis patients (HR28-day = 0.76, P = 0.008)." (PMID 40420582, 2025). "NF-κB transcription factor family members, including RELB, NFKB2, REL, and IRF1, predominantly control WARS1-induced gene expression networks, indicating recapitulating hyperinflammatory sepsis endotypes." (PMID 38177528, 2024). "Renal-expressed TNFR2 promotes renal monocyte recruitment by the IRF1 and IFN-β autocrine signaling, which may contribute to renal injury in sepsis." (PMID 35203474, 2022). "Subgroup analyses revealed heterogeneous effects among patients with different APACHE scores, suggesting that early prophylactic activation of IRF1 may preferentially benefit patients with severe sepsis but not those with mild sepsis." (PMID 40420582, 2025).
Crohn disease (11 papers, 2012 to 2025). A gastrointestinal disorder characterized by chronic inflammation involving all layers of the intestinal wall, noncaseating granulomas affecting the intestinal wall and regional lymph nodes, and transmural fibrosis. "The gene cluster on chromosome 5q31 harbors several immune related genes, including the interleukins IL3, IL5 and the interferon regulator IRF1, which have been associated with Crohn’s disease in the European population." (PMID 22606245, 2012). "As the 503F allele was positively selected during the process of human migration out of the Fertile Crescent, other sequence variants in IRF-1 that are linked to 503F and cause Crohn's disease “hitchhiked” along during a selective sweep." (PMID 23300552, 2012). "Amongst others, we identified a new, similar, genotype-dependent switch in preferred polyadenylation site for family member IRF1, with a probable link to Crohn's disease." (PMID 23818875, 2013). "Compatible with this interpretation was the high expression of GBP5 and IRF1 in VA, which was not further induced by NV, since GBP5 is induced in the M1 subset upon LPS/IFN-γ stimulation, upon HIV infection and in active Crohn’s disease and ulcerative colitis (UC) patients." (PMID 36282455, 2023).
esophageal cancer (11 papers, 2011 to 2025). A primary or metastatic malignant neoplasm involving the esophagus. "Furthermore, high expression levels of both FOXM1c and IRF1 were positively associated with low survival rate and predicted a poor prognosis of oesophageal cancer patients." (PMID 30485581, 2019). "In addition, high expression levels of FOXM1c and IRF1 were also significantly associated with poor prognosis and advanced stage of oesophageal cancer." (PMID 30485581, 2019). "While various studies have reported the anti-proliferative role of IRF1, there are also indications that IRF1 contributes to the proliferation and metastasis of tumor cells in cancers such as esophageal cancer and head and neck squamous cell carcinoma." (PMID 40025540, 2025). "IRF1 was uniformly identified to be significantly downregulated by FOXM1c insufficiency in three oesophageal cancer cell lines." (PMID 30485581, 2019). "To investigate the relationship between the expression levels of FOXM1c and IRF1 in clinical specimens, we collected 120 oesophageal cancer samples, which were classified as high or low stage based on their TNM classifications." (PMID 30485581, 2019). "We also found that there was a high correlation between FOXM1c and IRF1 in 120 oesophageal cancer specimens; more importantly, both FOXM1c and IRF1 were co‐overexpressed in oesophageal cancer patients in the advanced stage and with poor prognosis." (PMID 30485581, 2019). "The close correlation between FOXM1c and IRF1 levels was further determined in 120 oesophageal cancer specimens." (PMID 30485581, 2019). "FOXM1c modulates oesophageal cancer invasion and migration by regulating IRF1 transcription and subsequently MMP2/9 expression." (PMID 30485581, 2019). "Genetically altering FOXM1c expression strongly affected oesophageal cancer metastasis by regulating IRF1 transcription, thus resulting in a change in MMP2/9 expression." (PMID 30485581, 2019). "We further observed that both FOXM1c and IRF1 were positively correlated with poor prognosis and low survival rate in oesophageal cancer patients." (PMID 30485581, 2019). "In another investigation, 5q31.1 was reported to be lost in primary esophageal carcinoma, and was the smallest commonly deleted region in 57% of the specimens tested, implicating IRF-1 in the pathogenesis of this malignancy." (PMID 29599126, 2018). "It was reported that the expression of IRF-1 inhibited the growth of esophageal cancer cells and that IRF-1 had a potential effect as a tumor suppressor in esophageal cancer." (PMID 29136005, 2017). "Conversely, elevated expression of IRF-2 (an inhibitor of IRF-1 transcriptional activity) and high IRF-2/IRF-1 ratios were observed to be associated with worse prognosis in esophageal cancer." (PMID 21875439, 2011). "In conclusion, IRF1 serves a dual role in esophageal cancer." (PMID 39384770, 2024). "IRF1 acts as a tumor suppressor to inhibit esophageal cancer cell proliferation." (PMID 39384770, 2024). "Additionally, FOXM1c promotes esophageal cancer metastasis through transcriptional regulation of interferon regulatory factor 1 expression." (PMID 31072351, 2019). "Together, these results indicate that both FOXM1c and IRF1 were independent prognostic indicators and might be potential drug targets for oesophageal cancer." (PMID 30485581, 2019). "FOXM1c promotes the metastasis by transcriptionally targeting IRF1 and may serve as a potential prognostic predictor for oesophageal cancer." (PMID 30485581, 2019). "For the correct interpretation of these findings, it was important to test the so-called ‘two-hit hypothesis’ in relation to IRF-1 to confirm the role of this gene in esophageal carcinoma and stomach adenocarcinoma." (PMID 29599126, 2018).
esophageal cancer (continued). "In addition, based on the GEO public database analysis, we found that IRF1 expression in oesophageal cancer was significantly higher than that in paired normal tissues, indicating a positive correlation between IRF1 and oesophageal cancer progression (GSE23400)." (PMID 30485581, 2019). "Therefore, FOXM1c and IRF1 may be potential independent biomarkers for prediction of oesophageal cancer prognosis." (PMID 30485581, 2019). "In esophageal cancer, RNA–protein interaction assays have shown that CARINH interacts with ILF3 (Interleukin Enhancer Binding Factor 3) and DHX9 (DExH-Box Helicase 9) to control the expression of the CARINH and IRF1 locus via a feedforward mechanism." (PMID 39773901, 2025).